NEDD9 (neural precursor cell expressed, developmentally down-regulated 9)
Description:
Scaffolding protein which plays a central coordinating role for tyrosine-kinase-based signaling related to cell adhesion. As a focal adhesion protein, plays a role in embryonic fibroblast migration (By similarity). May play an important role in integrin beta-1 or B cell antigen receptor (BCR) mediated signaling in B- and T-cells. Integrin beta-1 stimulation leads to recruitment of various proteins including CRKL and SHPTP2 to the tyrosine phosphorylated form. Promotes adhesion and migration of lymphocytes; as a result required for the correct migration of lymphocytes to the spleen and other secondary lymphoid organs. Plays a role in the organization of T-cell F-actin cortical cytoskeleton and the centralization of T-cell receptor microclusters at the immunological synapse (By similarity). Negatively regulates cilia outgrowth in polarized cysts (By similarity). Modulates cilia disassembly via activation of AURKA-mediated phosphorylation of HDAC6 and subsequent deacetylation of alpha-tubulin. Positively regulates RANKL-induced osteoclastogenesis (By similarity). Required for the maintenance of hippocampal dendritic spines in the dentate gyrus and CA1 regions, thereby involved in spatial learning and memory (By similarity).
Synonyms: hEF1; CAS-L; CasL; CASS2; CAS2
Tractability: Antibody: its Gene Ontology location is reachable by antibodies, with high confidence; UniProt places it where antibodies can reach, with medium confidence. PROTAC: UniProt records ubiquitination sites on it; ubiquitination databases record sites on it; its protein half-life has been measured.
Gene: Protein-coding gene on chromosome 6 (11,183,298 to 11,382,348, reverse strand). Ensembl gene ENSG00000111859.
Subcellular location: Cytoplasm, cell cortex; Nucleus; Golgi apparatus; Cell projection, lamellipodium; Cytoplasm; Cell junction, focal adhesion; Cytoplasm, cytoskeleton; Cytoplasm, cytoskeleton, spindle pole; Cell projection, cilium; Cytoplasm, cytoskeleton, cilium basal body; Basolateral cell membrane; Cytoplasm, cytoskeleton, spindle (Enhancer of filamentation 1 p55)
Subcellular location (Human Protein Atlas): Cytosol; Nucleoplasm
Gene Ontology:
Molecular function: protein binding; protein tyrosine kinase binding
Biological process: cilium disassembly; positive regulation of cell migration; positive regulation of protein tyrosine kinase activity; positive regulation of substrate adhesion-dependent cell spreading; actin filament bundle assembly; cell adhesion; cell migration; cell surface receptor protein tyrosine kinase signaling pathway; cytoskeleton organization; integrin-mediated signaling pathway; learning or memory; lymphocyte migration into lymphoid organs; negative regulation of cell migration; positive regulation of dendritic spine maintenance; positive regulation of immunological synapse formation; positive regulation of lymphocyte chemotaxis; positive regulation of osteoclast differentiation; positive regulation of protein localization; regulation of actin cytoskeleton organization; signal transduction
Cellular component: ciliary basal body; cytoplasm; cytosol; focal adhesion; Golgi apparatus; mitotic spindle; nucleoplasm; nucleus; basolateral plasma membrane; immunological synapse; plasma membrane; spindle; spindle pole; cell cortex; cilium; cytoskeleton; lamellipodium
Genetic constraint (gnomAD): Loss-of-function variants: 22 observed, 72.8 expected, observed/expected ratio (o/e) 0.3, 90% interval 0.22 to 0.43. The upper end of that interval is the gene's LOEUF score, 0.43, which puts it in group 1 of 6, group 1 being the genes least tolerant of losing a copy. Missense variants: 904 observed, 1,067.7 expected, observed/expected ratio (o/e) 0.85, 90% interval 0.8 to 0.89. Synonymous variants: 383 observed, 423.93 expected, observed/expected ratio (o/e) 0.9, 90% interval 0.83 to 0.98.
Homologues: Orthologues: chimpanzee NEDD9 (99% identical), macaque NEDD9 (98% identical), rabbit NEDD9 (91% identical), dog NEDD9 (89% identical), mouse Nedd9 (89% identical), guinea pig NEDD9 (88% identical), rat Nedd9 (87% identical), pig NEDD9 (85% identical), tropical clawed frog nedd9 (54% identical), zebrafish nedd9 (47% identical), Drosophila melanogaster p130CAS (25% identical). Paralogues in human: BCAR1 (41% identical), CASS4 (24% identical), EFS (20% identical).
Diseases named in the same sentence as NEDD9 in open-access papers:
NEDD9 is named in the same sentence as 106 diseases in open-access papers, as found by Europe PMC text mining. Sharing a sentence is not in itself a finding about the gene and the disease. The quoted sentences say what the papers report.
breast cancer (50 papers, 2010 to 2025). A primary or metastatic malignant neoplasm involving the breast. "It was shown that increased expression of NEDD9 was associated with a worse prognosis in breast cancer and promotes cell invasion in aggressive breast cancer." (PMID 32887237, 2020). "Loss of NEDD9 impairs mammary tumor development by limiting the activation of multiple pro-oncogenic signaling proteins, including the binding partners FAK and Src." (PMID 27974675, 2017). "A series of studies have implicated the NEDD9 protein as a biomarker of invasive ability and an essential switch for pro-metastatic behavior in numerous types of cancer, including lung cancer, breast cancer and melanoma." (PMID 25646678, 2015). "High BCAR1 expression is linked to poor prognosis in breast cancer patients, while upregulation of NEDD9 contributes to the metastatic behavior of melanoma and glioblastoma cells." (PMID 21765937, 2011). "A noticeable point arising from this study is that high levels of NEDD9 expression were associated with the aggressive breast cancers, including TNBC and ERBB2-overexpressing subtypes." (PMID 21829474, 2011). "The neural precursor cell expressed, developmentally downregulated protein 9 (NEDD9) has also been linked to cancer and it is a component of the metastatic signatures of melanoma, breast cancer, glioblastoma, lung cancer, and head and neck squamous cell carcinoma." (PMID 38137332, 2023). "Since mammary intraepithelial neoplasia, including DCIS, is associated with an increased risk of breast cancer, these results suggest that NEDD9 upregulation might be pre-disposed to neoplastic transformation." (PMID 36831460, 2023). "The mechanisms underlying the up-regulation of p130Cas/BCAR1 and Nedd9 in breast cancer are still largely unknown." (PMID 25606587, 2014). "High expression of NEDD9 may therefore be a potential diagnostic marker for these subtypes of breast cancer." (PMID 21829474, 2011). "Interestingly, high levels of NEDD9 expression were associated with aggressive breast cancers, including ER−/PR−/Her2− subtype of invasive ductal breast cancers and Her2/neu-positive breast cancers." (PMID 21829474, 2011). "Some studies have confirmed that NEDD9 stimulates breast cancer cells invasion by influencing EMT and activating MMP." (PMID 39199304, 2024). "We report that NEDD9 is overexpressed in a significant subset of HER2+ breast cancers and correlates with a limited response to anti-HER2 therapy." (PMID 36831460, 2023). "In HER2+ human breast cancer cell lines, NEDD9 was upregulated compared to the control, and was correlated with proliferation." (PMID 36831460, 2023). "Here, we report that increased NEDD9 expression tightly correlates with the expression of HER2 protein in breast cancer patient biopsies and decreased anti-HER2 therapy response." (PMID 36831460, 2023). "NEDD9 (HEF1) plays an important role in cell attachment and division in mitosis, and promotes breast cancer development and colorectal cancer progression." (PMID 37445737, 2023). "Taken together, the findings support the theory that increased NEDD9 expression induced by HDAC4 inhibition promotes breast cancer cell mobility." (PMID 36604412, 2023). "The breast cancer tissue microarrays (TMAs), with breast patient biopsies, were analyzed for NEDD9 expression using a validated antibody to address this gap." (PMID 36831460, 2023). "NEDD9 is not an oncogene, however, it has been demonstrated recently that there are high level or activity changes of NEDD9 in a variety of cancer, including leukemia, colon cancer, and breast cancer." (PMID 36604412, 2023). "In contrast, depletion of NEDD9 using siRNA inhibited the invasive phenotype of breast cancer cells in vitro and in vivo." (PMID 36604412, 2023). "Both RAD50 and RAD52 are functionally involved in DNA repair, and their protein expression was largely correlated with the focal adhesion protein NEDD9 in breast cancer cells." (PMID 37445737, 2023).
breast cancer (continued). "miR-107 has a potential role in regulating NEDD9 in the invasion, migration and proliferation of breast cancer." (PMID 35887223, 2022). "The relations between NEDD9 and clinicopathological features and molecular subtyping of breast cancer were analyzed." (PMID 35549691, 2022). "Previous work on the crucial role of SOX2 in breast cancer cell migration showed that SOX2 upregulation in hypoxic conditions facilitated NEDD9 transcription and subsequent activation of HIF-1α expression." (PMID 32913192, 2020). "Here, we find that upregulation of SOX2 facilitated hypoxia-induced breast cancer cell migration via regulation of NEDD9 transcription and expression." (PMID 31462898, 2019). "Consistently, knockdown of NEDD9 by 3 siNEDD9 completely blocked the effect of hypoxia on breast cancer cell migration, as assessed in the wound-healing and transwell migration assays." (PMID 31462898, 2019). "The increase in the proportion of the 105 kDa isoform in MDA-MB-231 and 115 kDa isoform in MDA-MB-468 under hypoxia indicate a relative different increment of NEDD9 phosphorylation status in various types of breast cancer cells." (PMID 31462898, 2019). "Results from this study show that ZMYND10 suppresses breast cancer tumorigenicity by inhibiting the miR145-5p/NEDD9 signaling pathway." (PMID 31801619, 2019). "In further investigations, we identified a novel link between SOX2 and NEDD9 in the regulation of breast cancer cell migration under hypoxia." (PMID 31462898, 2019). "qPCR assay was performed to confirm the inhibitory effect of ZMYND10 on NEDD9 expression in breast cancer cells." (PMID 31801619, 2019). "Collectively, these results show that Rac1 is required for SOX2- and NEDD9-mediated breast cancer cell migration under hypoxia." (PMID 31462898, 2019). "Altogether, the results suggested that ZMYND10 is able to suppress migration and invasion of breast cancer cells by inhibiting NEDD9 expression." (PMID 31801619, 2019). "In this study, we found that ZMYND10 suppresses breast cancer tumorigenicity through upregulating miR-145-5p to inhibit the expression of oncogene NEDD9, which results in suppression of cell invasion and migration and breast cancer progression." (PMID 31801619, 2019). "We noticed here that hypoxia induced NEDD9 expression in a time-dependent fashion in breast cancer cells." (PMID 31462898, 2019). "NEDD9 downregulation has been shown to dramatically reduce cell invasion and metastasis in multiple tumors including breast cancer." (PMID 31801619, 2019). "Screening of differentially expressed genes in the focal adhesion pathway leads the focus to NEDD9 that is closely related to breast cancer metastasis." (PMID 31801619, 2019). "In breast cancer models the expression of the Cas family scaffold members NEDD9 (HEF1, Cas-L) or p130Cas (BCAR1) promotes phenotypes associated with epithelial-to-mesenchymal transition (EMT) in a Src kinase-dependent manner." (PMID 29464017, 2018). "Using breast cancer cell lines, McLaughlin and coworkers reported that NEDD9 depletion reduced MMP2 and MMP9, cell invasion and matrix degradation." (PMID 29876004, 2018). "Neural precursor cell expressed developmentally downregulated 9 (NEDD9) is a component of the metastatic signatures of melanoma, breast cancer, glioblastoma, lung cancer and head and neck squamous cell carcinoma (HNSCC)." (PMID 29876004, 2018). "Consistent with this role, NEDD9 was identified as a component of the metastatic signatures of HNSCC glioblastoma breast cancer lung cancer and melanoma." (PMID 29876004, 2018). "Overexpression of NEDD9 protein correlates with poor prognosis in cancers including breast cancer, glioblastoma, lung cancer and melanoma." (PMID 27974675, 2017). "NEDD9 is highly expressed in breast cancer, colorectal cancer and head and neck cancer, in which its expression levels are positively correlated to cancer cell migration, invasion, and metastasis." (PMID 28915595, 2017).
breast cancer (continued). "In MCF-7 mammary tumour cells, up-regulation of Nedd9 results in enhanced AurA activity leading to centrosomal and mitotic spindle abnormalities, whilst a weaker effect can be seen after changes of p130Cas/BCAR1 expression." (PMID 25606587, 2014). "Like p130Cas/BCAR1, Nedd9 is strongly over-expressed in human breast cancers with respect to normal tissue." (PMID 25606587, 2014). "As a consequence, Nedd9 overexpression in breast cancer cells leads to AurA protein stabilization and decreases the efficacy of AurA inhibitors." (PMID 25606587, 2014). "In this review, we summarize and discuss the most recent findings regarding the role of p130Cas/BCAR1 and Nedd9 in the normal mammary epithelium and in different breast cancer subtypes." (PMID 25606587, 2014). "Lastly, Nedd9 has been found over-expressed in claudin low breast cancers compared with other molecular subtypes." (PMID 25606587, 2014). "Noteworthy, in spite of their structural similarity, p130Cas/BCAR1 and Nedd9 exert both redundant and specific functions in breast cancer cells." (PMID 25606587, 2014). "The contribution of p130Cas/BCAR1 and Nedd9 to specific oncogenic pathways in different breast cancer subtypes is described in detail in the paragraphs below." (PMID 25606587, 2014). "Both p130Cas/BCAR1 and Nedd9 are abundantly expressed in human breast tumours and breast cancer cell lines." (PMID 25606587, 2014). "The relevance of the adaptor proteins p130Cas/BCAR1 and Nedd9 in breast cancer has been highlighted by numerous in vivo and in vitro studies." (PMID 25606587, 2014). "In claudin low breast cancer cell lines TGF-beta up-regulates Nedd9 expression by inducing Smad and MRTF-SRF protein binding to regulatory regions within the NEDD9 locus." (PMID 25606587, 2014). "Analysis of Nedd9 expression across different breast cancers has revealed a correlation of this gene with the TNBC subtype." (PMID 25606587, 2014). "NEDD9 acts as a positive regulator of EMT in breast cancer cell lines, and it is also involved in mammary gland tumorigenesis." (PMID 25414831, 2014). "This study revealed that depletion of Nedd9 impairs mammary tumour development by limiting the activation of multiple pro-oncogenic signalling proteins, including its binding partners Fak and Src as well as Ras downstream effectors." (PMID 25606587, 2014). "Over the past decade, p130Cas/BCAR1 and Nedd9 have emerged as key players in the control of many different aspects of mammary gland biology, including mammary epithelial cell homeostasis and mammary tumour cell behaviour." (PMID 25606587, 2014). "As well, cells from MMTV-PyMT; NEDD9-null mammary tumours exhibit pronounced genomic instability, which ultimately facilitates the selection of cells with a more aggressive phenotype." (PMID 25606587, 2014). "Nedd9 has also been identified as one of the key genes that mediate the switch from cohesive to single cell motility induced by TGF-beta during breast cancer cell dissemination." (PMID 25606587, 2014). "Recent studies showed that NEDD9 regulates TGFβ pathway in breast cancer and hepatocellular cancer and Wnt signaling in colorectal cancer." (PMID 24058594, 2013). "Up to now, NEDD9 was found to participate in cancer metastasis in glioblastoma, melanoma, and breast cancer." (PMID 24058594, 2013). "In the past several years, altered expression of scaffolding protein NEDD9 has emerged as contributing to cancer metastasis in multiple cancer types, such as breast cancer, glioblastoma, melanoma, lung and head and neck squamous cell carcinoma (HNSCC)." (PMID 24058594, 2013). "The fact that the NEDD9-null genetic background significantly limits mammary tumor initiation in mice strongly supports the notion of a key role of NEDD9 in promoting breast cancer progression and metastasis." (PMID 22984505, 2012).